MIR218-2 (microRNA 218-2)
Synonyms: hsa-mir-218-2; MIRN218-2; mir-218-2
Gene: MicroRNA gene on chromosome 5 (168,768,146 to 168,768,255, reverse strand). Ensembl gene ENSG00000207739.
Gene Ontology:
Biological process: miRNA-mediated post-transcriptional gene silencing
Cellular component: RISC complex
Homologues: Orthologues: chimpanzee ptr-mir-218-2 (100% identical), macaque mml-mir-218-2 (100% identical), dog MIR218-2 (98% identical), guinea pig MIR218-2 (98% identical), mouse Mir218-2 (95% identical), rat Mir218-2 (95% identical), pig ssc-mir-218b (75% identical), rabbit MIR218-2 (71% identical), tropical clawed frog xtr-mir-218-2 (65% identical), zebrafish mir218a-2 (60% identical). Paralogues in human: MIR218-1 (64% identical).